HGF (hepatocyte growth factor)
Diseases named in the same sentence as HGF in open-access papers (continued):
Sharing a sentence is not in itself a finding about the gene and the disease.
breast carcinoma (continued). "In pancreatic cancer cell lines, HGF/c-Met has been showed to transmit intracellular signal via MAPK pathway, and is essential to phosphorylate and stabilize TWIST1 in breast cancer." (PMID 27280289, 2016). "Encapsulated EGCG maintained its biological activity, being able to inhibit hepatocyte growth factor (HGF) and subsequent activation of cell signaling pathways responsible for cell invasion in breast cancer cell line MDA-MD-23." (PMID 27213442, 2016). "The cytotoxicity assay was performed using MDA-MB-231 breast cancer cells, cultured with 2 different doses of HVS (30 and 60 μM), in the presence of 40 ng/ mL HGF, to induce cell death and LDH release." (PMID 27086914, 2016). "Exposure to growth inhibitory concentrations of HVS markedly inhibited HGF-induced phosphorylation and activation of Akt and MAPK in MDA-MB-231 mammary cancer cells." (PMID 27086914, 2016). "Here, we used a combination of siRNA and pharmacologic approaches to demonstrate that key factors expressed in breast cancer, TGF-β and HGF, modulate CXCL1 expression in CAFs." (PMID 26252654, 2015). "Production of large amounts of the HGF activator (HGFA), stimulating expression of HGF in stromal cells, has been previously demonstrated in highly invasive breast cancer cells such as MDA-MB-231 that also overexpress the HGF receptor c-met." (PMID 25880005, 2015). "HGF induced activation and phosphorylation of c-Met in MDA-MB-231, MCF-7 and BT474 breast cancer cells in culture." (PMID 24849787, 2014). "At high concentrations, NK1 was found to induce proliferation in a breast cancer epithelial cell line and in BALB/MK cells, MCF-10A cells, and in BaF3 cells expressing MET, albeit at a lower level than HGF." (PMID 28548073, 2014). "These migration data showed an additive influence of HGF treatment and SOCS7 knockdown on the in vitro migration of both breast cancer lines." (PMID 25162020, 2014). "Among the various factors, HGF is found to confer substantial resistance to RAF and MEK inhibition by activation of the RTK Met in melanoma and breast cancers." (PMID 25057499, 2014). "HGF and its receptor, C-MET, are both critical mediators of breast cancer progression, and, like in many other solid organ cancers, both HGF and C-MET are highly expressed in breast cancer." (PMID 25162020, 2014). "STAT3 was activated by IL-6 in myeloma and prostate cancer cells, hepatocyte growth factor (HGF) and its receptor (c-MET) in leiomyosarcoma and breast cancer cells, and Src in breast cancer and melanoma cells." (PMID 24675568, 2014). "A complex variety of cytokines and growth factors such as TGF-β, hepatocyte growth factor (HGF), epidermal growth factor (EGF), and tumour necrosis factor α (TNFα) have been shown to influence MMP 9 induction by fibroblasts in breast cancer cells." (PMID 24800085, 2014). "In breast cancer, a negative regulatory deoxyadenosine tract element (DATE) composed of about 30 adenosines was described to be present in the HGF promoter." (PMID 24716444, 2014). "Recently, strong evidence supports the role for the hepatocyte growth factor (HGF) and its receptor in the development and progression of breast carcinoma." (PMID 24849787, 2014). "HGF and C-MET expression correlates with mammary tumour pathology, showing lowest expression levels in normal tissue and benign hyperplasia while increasing in ductal carcinoma in situ and showing highest expression in invasive breast carcinomas." (PMID 25162020, 2014). "Exposure to growth inhibitory concentrations of (-)-oleocanthal blocked HGF-induced phosphorylation and activation of Akt and MAPK in MDA-MD-231 mammary cancer cells." (PMID 24849787, 2014). "Here, we dissect the pathways used by highly metastatic breast carcinoma cell line MDA-MB-231, which are able to migrate and invade toward LPA, HGF and EGF." (PMID 24160245, 2013).
breast carcinoma (continued). "Our data, using a novel HGF signature and three independent tumor datasets, indicate that HGF/MET signaling is highly correlated with basal-like breast cancer subtype and worse overall survival in patients." (PMID 24025166, 2013). "HGF has also been shown to actively promote production of MT1-MMP in MDA-MB 231 cells, which further activated MMP2 and enhanced the invasiveness of breast cancer cells." (PMID 22242160, 2012). "HGF is able to induce CXCR4 expression and contributes to tumor cell invasiveness in breast carcinoma." (PMID 22242160, 2012). "Recently, a group of HER2-positive metastatic breast cancer tissues was examined by FISH for Met (n = 130) and HGF gene copy number (n = 84)." (PMID 23227361, 2012). "To do this, we determined the expression of HGF, c-Met and CXCR4 in breast cancer tissues by immunohistochemistry using corresponding antibodies, which revealed positive immunostaining of HGF, c-Met or CXCR4 in 197 cases of invasive breast carcinoma." (PMID 22242160, 2012). "In the present study, we demonstrated that HGF-induced activation of PKCζ increases CXCR4 expression and the migratory capacity of MDA-MB-436 breast cancer cells." (PMID 22242160, 2012). "To further confirm that HGF-induced cell migration occurs independently of Brk kinase activity, we tested the migratory status of MDA-MB-435 cells, a Brk-null, Met-positive breast cancer cell line with similarity to melanoma." (PMID 20687930, 2010). "Similarly, in a breast cancer model, normal fibroblasts that were irradiated and injected into the mouse mammary fat pad overexpressed TGF-β and hepatocyte growth factor (HGF), thereby supporting tumor initiation." (PMID 37966629, 2025). "HGF secreted by CAFs activates MET signaling, enhancing the colony-forming ability of cancer cells, and the use of HGF neutralizing antibodies can effectively reduce CAF-mediated breast cancer proliferation and invasion." (PMID 40890855, 2025). "Notably, elevated levels of CASP8, latency-associated peptide of transforming growth factor beta-1 (LAP TGF-β1), HGF, and ARG1 were observed among breast cancer patients diagnosed within 5 years of follow-up." (PMID 40665092, 2025). "Due to the small sample sizes for basal-like (n = 10) and HER2+ breast cancers (n = 7), we did not analyze associations between CCL2 and HGF in these subtypes." (PMID 40736024, 2025). "As CCL2, HGF and CCL2/HGF treatment of breast cancer cells led to differences in glucose metabolism, we examined for expression of glycolytic proteins over time, including glucose transporter 1 (GLUT1) and rate limiting enzymes HK2, lactate dehydrogenase (LDHA) and pyruvate kinase M (PKM)." (PMID 40736024, 2025). "How might interactions between breast cancer cells with the microenvironment regulate CCL2/CCR2 and HGF/MET signaling?" (PMID 40736024, 2025). "Further, biochemical studies of breast cancer cell lines from various subtypes could be helpful in clarifying the mechanisms through which CCR2 and MET overexpression regulates CCL2 and HGF signaling." (PMID 40736024, 2025). "In light of our results, targeting HGF, ANGPT, and PDGF pathways could provide an effective strategy to inhibit angiogenesis in breast cancer." (PMID 39302921, 2024). "Similar metabolic effects were found in MDA-MB 231 breast cancer cells and HGF-human gingival fibroblasts, but not in HeLa cancer cells." (PMID 39769112, 2024). "CAFs are known to predominantly secrete HGF, and activation of the MET receptor tyrosine kinase can enhance the invasiveness, epithelial‐to‐mesenchymal transition and the activation of multiple oncogenic pathways in breast cancer." (PMID 38445456, 2024). "Due to the intriguing correlation observed between NMDAR and MET in neurons, our previous investigation aimed to establish a connection between NMDAR and the HGF–MET pathway in the context of non-neuron cells such as breast cancer cells." (PMID 38201232, 2023).
breast carcinoma (continued). "For example, in some breast cancers and in human squamous cell carcinomas, Matriptase is responsible for cancer progression by increasing cell proliferation and invasiveness via an HGF (Hepatocyte growth factor)—cMET—pAKT pathway." (PMID 37566613, 2023). "Consequently, this facilitates DNA hypermethylation at the promoter region of microRNA-200a (miRNA-200a), stimulating the expression of hepatocyte growth factor (HGF) and epidermal growth factor receptor (EGFR) and promoting breast cancer progression." (PMID 36672839, 2022). "In 1995, serum HGF in hormone receptor positive or negative breast cancer patients (n = 134) was studied using ELISA." (PMID 35818030, 2022). "Notably, hepatocyte growth factor (HGF) was secreted by mammary ADSCs and acted as a downstream molecular of adipsin in mammary ADSCs to improve the CSC properties in breast cancer." (PMID 35701840, 2022). "To further confirm the role of CDCP1 in HGF signaling, we subsequently employed a low invasive/nonmetastatic breast cancer cell line T47D, which had no significant expression of either protein and no invasive activity." (PMID 35085554, 2022). "A clinical study showed that breast cancer patients subjected to radiotherapy and oral administration of EGCG exhibited reduced activation of MMP-9/MMP-2 accompanied with low serum levels of VEGF and hepatocyte growth factor (HGF)." (PMID 34208196, 2021). "Finally, the prognostic power of HGF and FGFR1 co-expression in basal breast cancers offers a new strategy for stratifying patients, as well as potential anti-TIC therapeutic targets that warrant further investigation." (PMID 33772015, 2021). "SPINT1, which is one of the Kunitz-type serine protease inhibitors and also known as HAI-1, can inhibit hepatocyte growth factor function via regulation of HGFA, matriptase, and hepsin to inhibit the migration, proliferation, and invasion of breast cancer, indicating a good prognosis." (PMID 33336077, 2021). "The dual MET/ALK inhibitor crizotinib showed a dose-dependent reduction of viability in various breast cancer cell lines after 48 h of treatment, with an IC50 of 5–10 μM18, which is similar to the IC50 obtained in our HGF-stimulated, crizotinib-treated chordoma cells." (PMID 34127734, 2021). "In breast cancer cells, hyperactivation of signaling pathways such as phosphoinositide 3-kinase–AKT– (PI3K/AKT/mTOR), MAPK, and hepatocyte growth factor (HGF)/Met (hepatocyte growth factor receptor (HGFR)) increases cell growth, proliferation, survival, and cancer hallmarks." (PMID 34768930, 2021). "Met interaction with Fis1 could also occur in other types of human cancer cells like HCC1806 breast cancer cells and HT29 colon cancer cells, which was analogously enhanced by HGF but diminished by crizotinib." (PMID 34848680, 2021). "Finally, we find that human TNBCs with mesenchymal characteristics are significantly enriched for HGF and FGFR1, and that co-expression predicts poor prognosis among basal breast cancer patients." (PMID 33772015, 2021). "As HGF activator inhibitors, serine protease inhibitor, Kunitz types 1 and 2 (SPINT1 and SPINT2) have been reported to be differentially expressed in breast cancer, but their prognostic significance and functioning mechanism remain unclear." (PMID 34381422, 2021). "Furthermore, our results showed that HGF was a downstream effector of Cfd and more effectively enhanced the CSC properties of breast cancer PDX cells than EGF." (PMID 34439392, 2021). "The remarkable difference in the prognostic value of HGF and c-MET compared to female breast cancer might result from differences in tumor and environment biology between male and female breast cancer." (PMID 32188473, 2020). "The human prostate cancer cell line DU145 and the human breast cancer cell line MDA-MB-231 were chosen to represent tumor cell lines with robust expression of total c-Met that did not secrete HGF; thus defined as paracrine-activated cell lines." (PMID 30719213, 2019).
breast carcinoma (continued). "By revealing TGFβ1 as a regulator of HGF/MET‐induced cell migration, our findings suggest TGFβ1 with its downstream mediators C‐ets‐1 and miR‐128‐3p as potential targets for therapy of basal‐like breast cancer." (PMID 30004628, 2018). "Breast cancer cells were cultured with various treatments for 72 h, following which the degree of invasion was assessed in both cell lines and quantified to reveal the effect of BFE on HGF-stimulated cells." (PMID 30314527, 2018). "HGF is believed to act as an initiation signal for the onset of EMT, which results in the upregulation of effector molecules, such as MMP-2 and MMP-9, and activation of STAT-3 to aid EMT and the metastatic dissemination of breast cancer cells." (PMID 30314527, 2018). "First, in breast cancer cells, growth factors other than EGF and HGF may trigger the activation of the MAPK signaling pathway, which includes ERK1/2." (PMID 30227653, 2018). "HGF stimulation did not appear to have any impact on the proliferation rate or the growth and formation of 3D spheroids within these breast cancer cells." (PMID 30314527, 2018). "HGF did not appear to have any bearing on the proliferation rate or spheroid formation of these breast cancer cells." (PMID 30314527, 2018). "We also report that the levels of STAT-3 and JAK-2 were found to be constitutively active in the BT549 breast cancer cell line and treatment with HGF and/or BFE had no bearing on the phosphorylational status." (PMID 30314527, 2018). "Concurrently, the isolated HGF secreting fibroblasts, which were co-cultured with EcSOD–overexpressing MDA-MB231 cells showed attenuated phenotype in their ability to promote naïve breast cancer cell invasion." (PMID 29296173, 2017). "The inhibition of mammary cancer cell growth was associated with the ability of HVS to disrupt c-Met receptor phosphorylation in response to its natural ligand HGF in MDA-MB-231, MCF-7, and BT474 breast cancer cells and inhibit the downstream c-Met effectors in culture." (PMID 27086914, 2016). "The phenotypes induced by inhibition of the Abl kinases were not restricted to breast cancer cells as treatment of the MDA-MB-435s melanoma cell line (also known as M14) with STI571 markedly inhibited HGF-induced invasion without inhibiting cell growth." (PMID 25946048, 2015). "A substantial increase in HGF and/or MET expression levels as a consequence of EGFR inhibition was shown to be responsible for the bypass of RTK inhibition in adult glioblastoma and breast cancer." (PMID 26496080, 2015). "Interestingly, data suggest that hepatocyte growth factor (HGF), the ligand for MET, and MET are expressed to a greater degree in triple-negative breast cancer relative to other breast cancer subtypes." (PMID 26123926, 2015). "Induction of mammary cancers has been reported in mice orthotopically grafted with TGF-β- and/or HGF-transfected fibroblasts, co-injected with apparently normal epithelial cells, highlighting the critical role of heterotypic interactions in the development of human breast malignancies." (PMID 25880005, 2015). "Ligands that bind to ErbB receptors were the most broadly active (every tested ErbB ligand elicited a significant response in at least 35 lines), followed by FGF-1/2, HGF, and IGF-1/2, consistent with the known importance of these ligands in breast cancer biology." (PMID 24655548, 2014). "Using breast cancer cell lines, studies showed that Erk5 plays roles in cell proliferation by regulating cyclin D1 and CDKs, epithelial mesenchymal transition, MET/HGF-induced migration and integrin/FAK-mediated metastasis." (PMID 24762669, 2014). "Further reports showed that HGF/C-MET downstream intermediate phospholipase Cγ-1 (PLCγ-1) overexpression was also observed in breast cancer, and specific PLCγ-1 inhibition was found to block breast cancer invasiveness." (PMID 25162020, 2014).
breast carcinoma (continued). "The present review will provide a brief summary of the increasing importance of the HGF/Met axis as an attractive target for cancer chemotherapy and the role of tocotrienols in suppressing Met activation, signaling and HGF-induced EMT in breast cancer cells." (PMID 26932375, 2014). "Rapamycin cooperated with HGF to increase the proliferation of the HCC1954 human breast cancer cell line, but did not produce significant differences in the signaling pathways examined." (PMID 24927123, 2014). "Similar, albeit less pronounced results were obtained with BT549 breast cancer cells, but under these conditions, neither HGF, rapamycin, nor HGF + rapamycin had significant effects on BT549 cell proliferation." (PMID 24927123, 2014). "To examine the molecular mechanism by which senescent MSCs stimulate breast cancer cell proliferation and migration, we assessed four cytokines (IL-6, VEGF, HGF and TNF-α) that are closely related to tumor progression by enzyme linked immunosorbent assay (ELISA)." (PMID 25419563, 2014). "Other ligands to which breast cancer cells commonly respond include FGFs, IGF/INS, and HGF." (PMID 24655548, 2014). "Therefore, the role of HGF on the proliferation and growth of MDA-MB-231, MCF-7 and BT-474 breast cancer cells was investigated." (PMID 24849787, 2014). "However, the IC50 values for (-)-oleocanthal treatment in HGF-free media were 16.2, 40.8 and 58.4 μM in MDA-MB-231, MCF-7 and BT-474 breast cancer cells, respectively." (PMID 24849787, 2014). "Shortage to less than 25 adenosines was necessary to obtain aberrant HGF expression in breast cancer cells and breast tissue, which normally does not express HGF." (PMID 24716444, 2014). "For instance, as tumours become more aggressive, heparanase activity is enhanced in myeloma, lymphomas or breast cancer, increasing both the number of exosomes released and the amount of syndecan-1, VEGF and HGF molecules exposed on their surface, making them more available for detection." (PMID 24223259, 2013). "Our results emphasize that HGF/MET signaling is important in basal-like breast cancer progression from early in the disease, but HGF has long been studied in invasive cancer biology and in normal development." (PMID 24025166, 2013). "Given the high expression of wound response genes in the tissue adjacent to cancer and the important role of HGF in normal ductal morphogenesis and invasive breast cancer, a better understanding of HGF/MET in progression of basal-like breast cancers is important." (PMID 24025166, 2013). "To determine whether the proteases required to activate pro-HGF were present in the breast cancer cells, we utilized a fibroblast cell line expressing pro-HGF (RMF-HGF)." (PMID 22788954, 2012). "The ligand for Met, HGF is not expressed in epithelial cells; and Met is not phosphorylated in gefitinib-sensitive breast cancer cell lines." (PMID 22788954, 2012). "Our current results show that Brk also enhances HGF-induced ERK5 activation, implicating both kinases (i.e., Brk and ERK5) downstream of Met receptor signaling in cell migration/invasion, and suggestive of breast cancer biology related to metastasis." (PMID 20687930, 2010). "Yamashita and colleagues found that in both human breast tumors and two breast cancer cell lines, HGF was not expressed or secreted." (PMID 20624308, 2010). "In this study, we demonstrate that HGF protein is not expressed or secreted in two breast cancer cell lines, SUM149 and SUM229." (PMID 20624308, 2010). "No significant changes in activation of p38 MAPK were observed upon HGF treatment of HaCaT cells or breast cancer cell lines (not shown); p38 MAPK was not further studied herein (except when included as a loading control)." (PMID 20687930, 2010). "This is the first report of EGFR and Met physically interacting and EGFR regulating Met activation in the absence of HGF in breast cancer." (PMID 20624308, 2010).